TGFBR1 (transforming growth factor beta receptor 1)
Diseases named in the same sentence as TGFBR1 in open-access papers (continued):
Sharing a sentence is not in itself a finding about the gene and the disease.
congenital heart disease (1 paper, 2023). A heart disease that is present at birth. "We report here on two families with various forms of congenital heart disease without aortopathy, in which we identified rare variants in TGFBR1." (PMID 37998513, 2023). "Taken together, we illustrate that variants in TGFBR1 can also lead to familial forms of non-syndromic congenital heart disease without aortopathy." (PMID 37998513, 2023). "In contrast, we report here on two TGFBR1 variants in two families in whom affected members have various forms of congenital heart disease, but no aortopathies, nor signs of extracardiac phenotype or phenotypes compatible with LDS." (PMID 37998513, 2023).
cutaneous squamous cell carcinoma (1 paper, 2016). "Here, the authors demonstrate that inactivating driver mutations in TGFBR1 and TGFBR2 occur in vemurafenib-induced and sporadic cutaneous squamous cell carcinomas." (PMID 27558455, 2016). "Using targeted sequence analysis and whole-exome sequencing (WES), we identify frequent mutation in both transforming growth factor-β (TGFβ) type 1 receptor (TGFBR1) and TGFβ type 2 receptor (TGFBR2) genes in human primary cutaneous squamous cell carcinoma (cSCC) samples." (PMID 27558455, 2016).
goiter (1 paper, 2021). Enlargement of the thyroid gland usually caused by lack of iodine in the diet, hyperthyroidism, or thyroid nodules. "Our data showed that expression of TGFBR1 was higher in goiter and PTC and lower in FA." (PMID 33905626, 2021). "TGFBR1 mRNA expression was upregulated in goiter and PTC, but downregulated in FA, distinguishing PTC from goiter (p=0.0049); PTC from FA (p<0.0001); and goiter from FA (p=0.0267)." (PMID 33905626, 2021).
hereditary connective tissue disorder (1 paper, 2025). "Loeys–Dietz syndrome (LDS) is a rare, systemic hereditary connective tissue disorder caused by mutations in transforming growth factor beta receptor 1 (TGFBR1) or TGFBR2." (PMID 40434616, 2025).
Inguinal hernia (1 paper, 2020). Protrusion of the contents of the abdominal cavity through the inguinal canal. "We discovered that PIK3R1, PTPN11, TGFBR1, CDC42, SOS1, and KRAS were the most essential inguinal hernia-causative proteins and UBC, GRB2, CTNNB1, HSP90AA1, CBL, PLCG1, and CRK were listed as the most commonly-involved downstream proteins." (PMID 31910207, 2020). "Five essential proteins (PIK3R1, PTPN11, TGFBR1, CDC42, and SOS1) and three downstream common proteins (UBC, GRB2, and CTNNB1) were found to be related to inguinal hernia development." (PMID 31910207, 2020). "Thus, proteins PIK3R1, CDC42, TGFBR1, PTPN11, UBC, CTFR, and SOS1 may play an important role in the inguinal hernia PPI network." (PMID 31910207, 2020).
leiomyosarcoma (1 paper, 2025). An uncommon, aggressive malignant smooth muscle neoplasm, usually occurring in post-menopausal women. "We sought to investigate the potential of miR-221, miR-320a, miR-133a, and miR-133b, along with their target mRNAs CDKN1B, TGFBR1, and IGF1R, as candidate biomarkers of leiomyosarcoma." (PMID 40630212, 2025). "The expression levels of miR-221, miR-320a, miR-133a, and miR-133b as well as their target mRNAs CDKN1B, TGFBR1, and IGF1R were assessed by quantitative real-time reverse transcription polymerase chain reaction (qRT-PCR) in tissue samples from 33 patients with leiomyosarcoma." (PMID 40630212, 2025). "The target mRNAs CDKN1B, TGFBR1, and IGF1R in 25 leiomyosarcoma tumor tissues were not significantly deregulated." (PMID 40630212, 2025).
lipid metabolism disorder (1 paper, 2024). "Compared with the Control group, the mRNA expression of Srebf2, Scap, Hmgcr, Soat1, Npc1, Snai3, Twist1, Itgav, Vegfc, and Tgfbr1 has higher expression in model group, indicating that there is lipid metabolism disorder in model mice." (PMID 38724499, 2024).
liver cirrhosis (1 paper, 2020). "Induction of liver cirrhosis with CCl4 significantly increased the expression of TGF-β1 and α-SMA; however, TGFBR1 expression was not significantly changed." (PMID 32928296, 2020).
meningioma (1 paper, 2012). A generally slow growing tumor attached to the dura mater. "TGFβ signaling pathway was also found activated in fibroblastic meningioma, since multiple key genes in the pathway were up-regulated in tumor tissues by qRT-PCR, including TGFB2 (4.95-fold), TGFBR1 (2.43-fold), SMAD2 (2.82-fold), and SMAD4 (3.24-fold)." (PMID 23285163, 2012).
muscular dystrophy (1 paper, 2020). Muscular dystrophy (MD) refers to a group of more than 30 genetic diseases characterized by progressive weakness and degeneration of the skeletal muscles that control movement. "This suggests that solely blocking Tgfbr1 and concomitant inhibition of TGF-β signalling may be sufficient to reduce fibrosis in muscular dystrophy." (PMID 32041253, 2020).
myopia (1 paper, 2021). "After correction for confounding factors (gender, age, near work time, and outdoor time), binary logistic regression analysis indicated that the TGFBR1 rs10760673 G > A variant was associated with positive myopia progression." (PMID 33996791, 2021). "First, the rs10760673 SNP of TGFBR1 was significantly associated with the progression of myopia (OR = 1.536, P = 0.008) and increases in AL and AL/CRC (β = 0.03, P = 0.011; β = 0.003, P = 0.032, respectively)." (PMID 33996791, 2021). "Additionally, a GWAS demonstrated an association of alterations in TGFBR1 with adult myopia." (PMID 33996791, 2021). "Multivariate regression analysis was used to assess the effect of the TGFBR1 rs10760673 and TGFB2-AS1 rs7550232 variants on the occurrence and progression of myopia." (PMID 33996791, 2021). "Associations of the variants of the TGFBR1 and TGFB2-AS1 genes with myopia may be mediated by the TGF-β signaling pathway; this hypothesis requires validation in functional studies." (PMID 33996791, 2021). "In summary, we demonstrated that the rs10760673 SNP of TGFBR1 and the rs7550232 SNP adjacent to TGFB2-AS1 may be new susceptibility loci for the progression and onset of myopia in Chinese school-aged children, respectively." (PMID 33996791, 2021). "However, the relationships between TGFBR1 variants and myopia were not investigated in school-aged children." (PMID 33996791, 2021). "Thus, the TGFBR1 gene may influence the progression of myopia and an increase in AL and AL/CRC, which are likely mediated by the TGF-β signaling pathway." (PMID 33996791, 2021).
omphalocele (1 paper, 2024). Omphalocele is an embryopathy classified in the group of abdominal celosomias and is characterized by a large hernia of the abdominal wall, centered on the umbilical cord, in which the protruding viscera are protected by a sac. "Another prominent phenotype of Tgfbr1-cKO fetuses was the presence of an omphalocele [5/5 at E16.5]." (PMID 38509075, 2024).
papillary thyroid cancer (1 paper, 2021). "We genotyped TGFB1, TGFBR1, and TGFBR2 SNPs in 157 papillary thyroid cancer (PTC) patients and 200 healthy controls." (PMID 33905626, 2021).
Pleural effusion (1 paper, 2007). The presence of an excessive amount of fluid in the pleural cavity. "Four new Tgfbr1 transcript variants were found in pleural effusion-derived tumor cells." (PMID 17705854, 2007).
psoriasis (1 paper, 2025). An autoimmune condition characterized by red, well-delineated plaques with silvery scales that are usually on the extensor surfaces and scalp. "One exception at the late time point was Tgfbr1, part of the disease promoting signaling in psoriasis, which was significantly downregulated." (PMID 41341581, 2025).
rectal cancer (1 paper, 2009). A primary or metastatic malignant neoplasm that affects the rectum. "On the other hand, TGFBR1*6A allele carriers were more prevalent among colon (proximal plus distal) cancer patients than rectal cancer patients (p = 0.024)." (PMID 19538729, 2009). "Interestingly, there was a significant difference in the frequency of the TGFBR1*6A allele between colon and rectal cancer cases." (PMID 19538729, 2009).
retinal degeneration (1 paper, 2021). Degeneration of the retina. "Recently, several studies reported that TGFBI variants and TGFBR1 polymorphisms are related to alleviating cone death in RP, and to retinal degeneration in AMD." (PMID 33946315, 2021).
Sepsis (1 paper, 2022). Sepsis is defined as life-threatening organ dysfunction caused by a dysregulated host response to infection. "However, the current studies on TGFBR1 in animal models of sepsis are scarce and deserve further exploration." (PMID 36188533, 2022). "Considering the importance of this pathway for sepsis and ferroptosis, we chose these key ferroptosis-related DEGs for subsequent analyses: MAPK14, VEGFA, TGFBR1, and DUSP1." (PMID 36188533, 2022). "In addition, we constructed a Cox proportional hazard model using MAPK14, VEGFA, TGFBR1, and DUSP1: they influenced survival within 28 days in sepsis patients, which emphasizes their importance in sepsis pathogenesis." (PMID 36188533, 2022). "We identified four ferroptosis-related genes (MAPK14, VEGFA, TGFBR1, DUSP1) that may influence the pathological progression of sepsis and the resulting organ dysfunction." (PMID 36188533, 2022). "No studies have shown that MAPK14, VEGFA, TGFBR1 and DUSP1 regulate ferroptosis in sepsis." (PMID 36188533, 2022).
serous ovarian cancer (1 paper, 2022). "We performed the qRT-PCR analysis of TGFβ components (TGFB1, TGFB2, TGFBR1, TGFBR2), Wnt5A/ROR1/ROR2, and Hippo-related genes (YAP1, TAZ, CCN1, and CCN2) in serous ovarian cancer subtypes (LGSOC, HGSOC, BLSOC) compared to the normal ovary." (PMID 35053353, 2022).
squamous cell carcinomas of the skin (1 paper, 2020). "Somatic TGFBR1 mutations are common in sporadic squamous cell carcinomas of the skin." (PMID 33256177, 2020).
status epilepticus (1 paper, 2021). Status epilepticus is defined as a continuous seizure lasting more than 30 min, or two or more seizures without full recovery of consciousness between any of them. "To test this hypothesis, here we assessed in a mouse model of TLE whether aberrant albumin-mediated TGFβR1/ALK5 signaling upon kainate-induced status epilepticus (SE) induces astrocyte uncoupling and epileptogenesis." (PMID 34025561, 2021).
sterility (1 paper, 2011). "Because Amhr2 is also expressed in mesenchyme-derived tissues in the oviduct and uterus, we examined whether the observed sterility is a phenotypic consequence of conditional knockout of Tgfbr1 in the oviduct and/or uterus." (PMID 22028666, 2011).
testicular germ cell tumor (1 paper, 2022). A germ cell tumor arising from the testis. "Additionally, UPF3B expression was positively correlated with most immunoinhibitors, including TGFBR1, IL10RB, CD160, CD274, TIGIT and PDCD1 in UVM, OV, KIHC, and LIHC, but negatively associated with the expression of majority genes in STAD and Testicular Germ Cell Tumors (TGCT)." (PMID 36194583, 2022).
thyroid nodule (1 paper, 2021). A small circumscribed mass in the THYROID GLAND that can be of neoplastic growth or non-neoplastic abnormality. "First, in this study, we aimed to investigate the role of TGFB1, TGFBR1, and TGFBR2 SNPs in the susceptibility to thyroid nodules malignancy and their correlation to clinical and anatomopathological characteristics." (PMID 33905626, 2021). "In addition, evaluating TGFB1 and TGFBR1 mRNA levels may be useful to characterize thyroid nodules malignancy." (PMID 33905626, 2021). "Evaluation of TGFB1 and TGFBR1 mRNA levels may be useful to identify malignancy in thyroid nodules." (PMID 33905626, 2021).
tongue cancer (1 paper, 2015). A malignant neoplasm affecting the tongue. "The expression and activation of EGFR increased when the tongue cancer cells CAL27 were transfected with TGFBR1 and/or PTEN in siRNA." (PMID 25723392, 2015).
tongue tumors (1 paper, 2013). "Expression of the IL-13 receptors was significantly higher in the tongue tumors from the Tgfbr1/Pten 2cKO mice (P value < 0.0001) when compared with the normal tongue tissue in which TGFBR1 and PTEN was not genetically deleted." (PMID 23421960, 2013).
type 2 diabetes (1 paper, 2007). "In addition, it was also noted that TGFBR1 (transforming growth factor-β receptor 1), which is an anti-inflammatory cytokine that inhibits the production of pro-inflammatory cytokines such as IL-6 and TNF-α was found to be up regulated in type 2 diabetes, most probably as a compensatory mechanism." (PMID 18078524, 2007).
uterine tumors (1 paper, 2023). "We profiled the data from uterine tumors deposited to the cBioPortal of Cancer Genomics for mutations of the TGFβ signaling pathway and identified several mutations in TGFβ-related receptors (TGFBR1, TGFBR2, ACVR1B, ACVR1C, ACVR2A, ACVR2B) and transcription factors (SMAD2, SMAD3, SMAD4)." (PMID 36906706, 2023).
vascular malformation (1 paper, 2018). A non-neoplastic disorder that is the result of defects of vascular morphogenesis. "However, at present and with the methods used, we are unable to differentiate hemorrhagic events in the mother of index patient reflecting the consequences of a TGFBR1-related vascular malformation or resulting from another cause." (PMID 30219046, 2018).
tumor (318 papers, 1996 to 2026). "Further, Microdissected tumor DNA from MSSE patients with constitutional TGFBR1 mutations reveals somatic loss of heterozygosity at the TGFBR1 locus, with the mutant allele retained, suggesting that TGFBR1 acts as a tumor suppressor gene." (PMID 40612107, 2025). "(see Section 3), PanIN progression mechanisms involve mutations in tumor-suppressing genes that lead to the activation of TGFβ signaling pathways (SMAD4/TGFBR1/TGFBR2)." (PMID 35565450, 2022). "Upregulation of S100a4 in TGFBR1-CA ovaries is likely associated with tumor formation, as S100a4 is implicated in multiple cellular and inflammatory events that promote tumorigenesis." (PMID 35565312, 2022). "Analysis of DNA from micro-dissected tumors from MSSE patients with constitutional TGFBR1 mutations shows somatic loss of heterozygosity at the TGFBR1 locus with retention of the mutant allele consistent with TGFBR1 behaving as a tumor suppressor gene." (PMID 33256177, 2020). "If mutations in TGFBR1, which lies at the telomeric end of the haplotype, and rare variants at the centromeric end of the haplotype are required for tumor development, ascertainment of affected individuals will select for the intact haplotype." (PMID 33256177, 2020). "Our recent studies have confirmed that the TGF-β pathway acts as a potent tumour suppressor pathway in cSCC with mutational inactivation of TGFBR1 and/or TGFBR2 occurring in ~40% of cSCC tumours." (PMID 30202019, 2018). "Direct follow up studies, particularly on ROF mutations in the tumor suppressors TGFBR1 and CHEK2 will be necessary before these mutations can be confirmed as bona fide cancer drivers." (PMID 28743916, 2017). "Follow up analysis of one miRNA selectively excluded via SEVs, miR-142-3p, showed that its release leads to both increased growth in donor cells and enhanced tumor supporting potential in cells in associated stroma, both via altered expression of TGFBR1." (PMID 28146434, 2017). "The tested mutations are from four genes, including two tumor suppressors (TGFBR1 and CHEK2) and two oncogenes (KDR and ERBB2)." (PMID 28743916, 2017). "Conditional loss of the tumour suppressor Tgfbr1 in epithelial cells, which abrogates TGF‐β signalling, leads to accumulation of TGF‐β1 ligands in stromal cells." (PMID 28401653, 2017). "In this study, we found that both highly recurrent (CHEK2 K373E) and rare point mutations (CHEK2 S372F/Y and A392V, TGFBR1 S241L and L354P) in tumor suppressors can also cause loss- or reduction-of-function." (PMID 28743916, 2017). "Conversely, increased excretion of miR-142-3p via donor cell SEVs and uptake by recipient endothelial cells was found to reduce TGFBR1 activity and cause tumor-promoting changes in these cells in vitro and in vivo." (PMID 28146434, 2017). "These analyses indicate that potentially damaging mutations in TGFBR1 occur early in 25% of tumours harbouring these mutations and in 42% of tumours harbouring potentially damaging TGFBR2 mutations." (PMID 27558455, 2016). "Taken together these data suggest that cells with mutational activation of BRAF, require TGFBR1 for efficient colony formation and that TGFβ would predictably function as a tumour promoter." (PMID 27835901, 2016). "High TGFBR1 mRNA levels in tumours were associated with poorer clinical outcomes for patients diagnosed with small (diameter ≤2 cm) tumours." (PMID 26703884, 2015). "Higher TGFBR1 mRNA levels were associated with poorer overall survival in the first 3 years, especially for the patients with small (diameter ≤2 cm) tumours." (PMID 26703884, 2015). "Using two Tgfbr1/Pten 2cKO mice, each with multiple tumor sites, an IC50 (the concentration of drug causing 50% inhibition of protein synthesis) ranging between 45–100 ng/ml was determined for IL-13-PE." (PMID 23421960, 2013). "We have previously mapped TGFBR1 to 9q22, and our search for TGFBR1 tumor-specific mutations led us to the discovery of a polymorphic allele of the type I receptor, TGFBR1*6A (6A)." (PMID 20500843, 2010).